CD40 (CD40 molecule)
Diseases named in the same sentence as CD40 in open-access papers (continued):
Sharing a sentence is not in itself a finding about the gene and the disease.
rheumatoid arthritis (52 papers, 2007 to 2026). A chronic, systemic autoimmune disorder characterized by inflammation in the synovial membranes and articular surfaces. "CD40 was associated with an increased risk of rheumatoid arthritis, thyrotoxicosis, and Graves’ disease." (PMID 41292233, 2025). "Rs4810485-T (CD40 locus) was associated with multiple autoimmune disorders, including “rheumatoid arthritis” (OR = 0.85, p = 5.7 × 10−9), “inflammatory bowel disease” (OR = 1.08, p = 4.6 × 10−10) and “multiple sclerosis” (OR = 1.08, p = 1.8 × 10−5)." (PMID 39006426, 2024). "We observed that genetic predisposition to higher plasma CD40 levels was associated with increased rheumatoid arthritis risk, consistent with evidence from both animal models and humans implicating the CD40 pathway in rheumatoid pathogenesis." (PMID 37563310, 2023). "We observed a similar phenomenon for CD40, with genetic predisposition to higher CD40 increasing risk of rheumatoid arthritis but protecting against IBD and multiple sclerosis." (PMID 37563310, 2023). "For example, the MS CD40 risk variant of SNP rs6074022 is protective for rheumatoid arthritis, and monoclonal antibodies to CD40 are effective for the latter, but exacerbate disease in the former." (PMID 28458668, 2017). "Recently, genome-wide association studies revealed an association at the CD40 locus with rheumatoid arthritis and multiple sclerosis." (PMID 25426283, 2014). "We thank the Rheumatoid Arthritis Consortium International (RACI) for making genetic data available for fine-mapping the CD40 risk locus." (PMID 23696745, 2013). "Recently, genome-wide association surveys have identified the association at the CD40 locus with rheumatoid arthritis and multiple sclerosis." (PMID 21976957, 2011). "Multiple candidate gene studies have also identified and validated the association of several SNPs in CD40 with autoimmune or autoinflammatory diseases including Graves’ disease, Crohn's disease, multiple sclerosis, and rheumatoid arthritis." (PMID 21976957, 2011). "However, the MR associations for these diseases had the opposite direction of effect compared with rheumatoid arthritis; that is, genetic predisposition to lower plasma CD40 levels was associated with higher risk of IBD and multiple sclerosis." (PMID 37563310, 2023). "Recently, a number of polymorphisms in the gene encoding CD40 gene have been identified and a relationship between the CD40 gene polymorphisms and risk of different autoimmune and inflammatory diseases, such as multiple autoimmune diseases, Graves’ disease and rheumatoid arthritis has been reported." (PMID 26474561, 2015). "Moreover, genetic studies have recently documented an important association between rheumatoid arthritis and CD40 variants, supporting the relevance of CD40 for inflammatory disease development." (PMID 20626864, 2010). "Platelet receptors such as CD40, GPIb/IX/V, and selectins have all been implicated in perpetuation of atherosclerosis, rheumatoid arthritis (RA), and tumors." (PMID 28932736, 2017). "Previously, we identified a common variant in the CD40 locus as associated with risk of rheumatoid arthritis (RA)." (PMID 23696745, 2013). "PheWAS analysis indicated that CD40 and Furin have detrimental effects on rheumatoid arthritis, AF, and other heart diseases." (PMID 41292233, 2025). "Our results revealed pathways that are known to be therapeutically important and new putative drug targets, including CD40 in rheumatoid arthritis, lymphotoxin-α (LTA) in multiple sclerosis and the chemokine CXCL5 in UC." (PMID 37563310, 2023). "A genetic investigation has connected CD40 and NF-κB pathway with rheumatoid arthritis, indicating that both molecules play a critical role." (PMID 37331977, 2023). "Although there are currently no trials of therapy targeting CD40L or ICOS in SSc patients, a promising study in patients with rheumatoid arthritis using of an anti-CD40 antagonist Mab leads to a decrease in activated B-cells and autoantibody production." (PMID 34461933, 2021).
rheumatoid arthritis (continued). "BI 655064, another antagonistic anti-CD40 antibody was safely tested on healthy volunteers, yet failed to meet the primary endpoint (clinical improvement) in patients with rheumatoid arthritis." (PMID 33198327, 2020). "Downregulation of the expression of inhibitory CD32b on B cells of patients with rheumatoid arthritis can be a regulatory response to increased B cell activating stimuli, such as CD40 engagement on MBC." (PMID 33505402, 2020). "One example is an IFNɣ-specific promoter usage QTL for the CD40 gene that colocalises with a GWAS signal for rheumatoid arthritis." (PMID 30618377, 2019). "(D) Colocalisation between a GWAS hit for rheumatoid arthritis (RA) and IFNɣ-specific tuQTL at the CD40 locus." (PMID 30618377, 2019). "One such example was the CD40 pathway in rheumatoid arthritis." (PMID 37563310, 2023). "In four cases, our top SNV had been associated with an inflammatory disease in previous GWAS: rs113010081/CCL4 with inflammatory bowel disease, rs1569723/CD40 with Crohn’s disease, rs4239702/CD40 with rheumatoid arthritis and rs11230563/CD6 with ulcerative colitis." (PMID 31727947, 2019). "One meta-analysis showed a significant association between the CD40 rs4810485 T allele and rheumatoid arthritis (RA) However, so far, no relevant research has addressed the association between CD40 genetic variants and HCV infection susceptibility or outcomes." (PMID 31615434, 2019). "However, the directionally discordant effects we observed of CD40 on rheumatoid arthritis versus multiple sclerosis and IBD raises the possibility of triggering other forms of immune-mediated diseases as a side effect of anti-CD40 therapy." (PMID 37563310, 2023). "Moreover, it is capable of increasing the surface expression of co-stimulatory molecules, such as CD54, CD40, and CD80, and it also enhances B-cell proliferation and inhibits neutrophil apoptosis in rheumatoid arthritis." (PMID 37373251, 2023). "Although genetic and non-genetic studies in mouse and human implicate the CD40 pathway in rheumatoid arthritis (RA), there are no approved drugs that inhibit CD40 signaling for clinical care in RA or any other disease." (PMID 23696745, 2013). "Moreover, circulating autoreactive memory B cells in rheumatoid arthritis (RA) showed a higher expression of the stimulatory receptor CD40 compared to nonautoreactive B cells." (PMID 39435875, 2025).
lymphoma (51 papers, 2006 to 2025). A malignant (clonal) proliferation of B- lymphocytes or T- lymphocytes which involves the lymph nodes, bone marrow and/or extranodal sites. "Due to its well-characterised role in driving lymphoma pathology, most mechanistic models of lymphoma encode regulation of a single NF-κB component by cell surface receptors such as CD40 and BCR signalling." (PMID 40613779, 2025). "Anti-CD40 or anti-CD20 therapy has also been demonstrated to reduce the risk of malignant lymphomas induced by EBV." (PMID 36680271, 2023). "Notably, a lower sensitivity to chemotherapeutic drugs (CHOEP) with ~3-fold higher relative IC50 was observed in ZNF217KO cells, suggestive for a resistance mechanism caused by CD40 stimulation, which has been described in lymphoma cells before." (PMID 37648814, 2023). "A study on T cell lymphoma showed that a CD40 antagonist also has tumor-killing effects, causing a rapid cytotoxic T cell response independent of helper T cells which expanded by tenfold over five days, eradicating lymphoma in mice." (PMID 36429020, 2022). "Autologous CD40-activated B-cells loaded with total RNA derived from autologous lymphoma cells were administered as an adjuvant to canine patients with lymphoma after achieving a complete response with chemotherapy." (PMID 39943162, 2025). "In our studies, higher levels of this activated DN2 subset (clusters 2,16, CD11C + CD21−HLA-DR + CD40+) were found in HC than in lymphoma patients." (PMID 40630518, 2025). "Growth-inhibitory effects of CD40 stimulation have been previously observed in several lymphoma and carcinoma cell lines in vitro." (PMID 37648814, 2023). "In stratified analysis by tumor subtype, we did not determine any significant associations between EVs bearing PD-L1, CD40, FasL, IL-6Rα, B7-H3, CD40L, ICAM-1 or CD20 with DLBCL, BL, and NOS lymphoma subtypes." (PMID 37809067, 2023). "Finally, we analyzed whether RelB-deficient LMP1/CD40 mice still develop lymphomas." (PMID 36110848, 2022). "Alternatively, a CD19-targeted and CD123-targeted CAR-T cell platform was developed with “always on” MyD88/CD40 signaling, which yielded robust anti-tumor activity in lymphoma and leukemia mouse models." (PMID 35053463, 2022). "In a clinical trial, autologous CD40-activated B-cells loaded with total RNA from autologous lymphoma cells were administered to 19 dogs with NHL as an adjuvant, following induction of a complete response with chemotherapy." (PMID 34513964, 2021). "We also showed higher levels of total PD-L1 expression by immunoblotting and of PD-L1 exported to the membrane by flow cytometry on LMP1/CD40 lymphoma cells from those mice than on B-cells from age related CD19_Cre mice." (PMID 31382969, 2019). "CD19, CD22, CD37, and CD40 have been identified, thanks to lymphoma molecular profiling, and are currently under investigation for the development of new antibody-based treatments." (PMID 30583481, 2018). "CD40Apt, a 2-fluoro-RNA aptamer against CD40, has shown antitumor effect on CD40-expressing A20 lymphoma cells in vitro and in vivo." (PMID 29562664, 2018). "The prognostic significance of CD40 expression on lymphoma cells and/or the bone marrow stromal cells as well as the impact of CD40-related BCR signaling are areas of ongoing investigation." (PMID 25355407, 2014). "Using our approach, we constructed a predictor of sensitivity to dacetuzumab, an investigational drug for CD40-expressing malignancies such as lymphoma using genomic measurements of cell lines treated with dacetuzumab." (PMID 20979617, 2010). "SGN-40 is a therapeutic antibody targeting CD40, which induces potent anti-lymphoma activities via direct apoptotic signalling cells and by cell-mediated cytotoxicity." (PMID 19066610, 2009). "The purpose of this study was to investigate the effect of CD40L on the apoptosis of CD40-expressing carcinomas and lymphoma cell lines induced by a variety of cytotoxic agents." (PMID 16545138, 2006).
lymphoma (continued). "Furthermore, our study identifies CIITA, LYZ, MBL2, and CD40 as potential therapeutic targets for various types of lymphoma treatment." (PMID 40360443, 2025). "Anti-CD40 antibody treatment also decreases the number of lymphoma cases produced by wild-type EBV." (PMID 37297008, 2023). "Moreover, continuous CD40-stimulation of lymphoma cells contributes to lymphoma cell survival, proliferation and drug resistance." (PMID 36110848, 2022). "We have previously found, that the pattern of signal activation is highly consistent in premalignant B cells from LMP1/CD40 mice, but varies considerably in lymphomas arising in different mice (including activation of the canonical NF-ĸB pathway in some lymphomas)." (PMID 36110848, 2022). "Indeed, soluble and membrane bound CD40L, as well as CD40 agonists, have been reported to exert opposite biological activities on lymphoma cell line proliferation and survival in previous studies." (PMID 16545138, 2006). "Also, Karpas422 cells appeared to be less efficiently killed by transgene expressing LOAd703 virus, which could likewise be explained by a stimulation of the lymphoma cells through CD40L/CD40 signaling." (PMID 33666760, 2021). "Additionally, the increased expression of CD40 and PD‐L1 argues for a role of HL‐secreted factors in the reprogramming of monocytes/ Mφ to further support the capacity of HL cells to suppress, for instance, T‐cell‐mediated anti‐lymphoma responses." (PMID 31825135, 2020). "In a report, anti-CD40 antibodies were administered to SCID mice that had been depleted on NK cells and engrafted with several EBV lymphoma cell lines, which express CD40 as a surface marker." (PMID 36680271, 2023). "These mutations have the common effect to disrupt the interactions between lymphoma cells and the immune microenvironment, via decreased antigen presentation and responsiveness to IFN-γ and CD40 signaling pathways." (PMID 35071240, 2021). "A number of new specific antibodies, including the anti-CD22, anti-CD40, anti-CD19, anti-CD19/CD3, and anti-CD37 antibodies, are currently used for alternative antibody-based therapy in lymphomas." (PMID 30583481, 2018). "The signaling pathway induced by anti-CD40, as we reported with normal B cells is distinct from and synergistic with anti-CD20 mAbs like rituximab, and can promote increased lymphoma cell death." (PMID 25324844, 2014). "GSEA also revealed up-regulation of a previously-defined, CD40-regulated, mature B-cell-specific gene expression signature, in the CYCLON-knockdown compared to control lymphoma Raji BL cells." (PMID 23828858, 2013). "Although significantly lower levels of CD20+CD27+CD24+CD40+CXCR4+CXCR5+ B cells were observed in MC14 of HIV+ pre-NHL (cART-naïve) samples, these cells had a potential pre-lymphoma phenotype as they expressed both cMYC and AICDA compared to HIV+ cART-naïve and HIV-negative samples." (PMID 39324141, 2024). "The CD20+CXCR4hiCD24+CXCR5+CD40+CD4+ B-cell population in MC23 of HIV+ pre-NHL (cART-naïve) samples displayed a mature and activated phenotype (IgM+HLADR+) with a potential pre-lymphoma feature as it expressed AICDA compared to MC23 of HIV+ cART-naïve samples." (PMID 39324141, 2024). "Previous studies indicated that early lymphomagenesis in lymphomas is a process related to CD4 + T cells stimulated by H. pylori antigens, and the proliferation of B-cell gastric lymphoma is dependent on CD40-mediated signaling, Th2 activities, co-stimulatory CD80, and CD86." (PMID 34980267, 2022). "CD40, TNF-RII or IL-6Rα on EVs may facilitate communication between lymphoma cells and distant immune cells of the tumor microenvironment." (PMID 35655072, 2022). "Further analysis of lymphoma development in these mice revealed that monoclonal B cell populations occurred earlier and with a higher incidence in LMP1/CD40 mice in comparison to LMP1/CD40//RelB-KO mice." (PMID 36110848, 2022).
lymphoma (continued). "L.CD40 mice are a model of marginal zone spleen B cell indolent lymphomas without plasma cell differentiation but with NF-κB activation." (PMID 34017329, 2021). "TFH cells can have a dual effect on lymphoma B cells, especially of GC origin, because of their physiologic function to provide pro-survival signals (e.g. via CD40L:CD40) only to B cells that have optimally re-arranged their Ig genes and to restrain the growth of the other suboptimal clones." (PMID 35071240, 2021). "The preferred interaction between CD40 and TRAILR2 may thus be common to lymphoma cell lines and primary cells." (PMID 28182009, 2017). "Dacetuzumab (SGN-40), a non-blocking, partial agonist, humanized IgG1, anti-CD40 monoclonal antibody, has previously demonstrated anti-lymphoma activity in a phase I study." (PMID 24919462, 2014). "In LMP1/CD40 mice, lymphoma incidence and expansion was reduced in the absence of RelB." (PMID 36110848, 2022). "In addition, necrotic cells obtained from mouse EL-4 (lymphoma) or WHEI 164 (fibrosarcoma) cell lines were unable to trigger CD40 expression or TNF (non-detectable values) in microglia." (PMID 18844999, 2008). "NF-κB signaling driven by constitutive CD40 activation also cooperates with transgenic λ-Myc to induce lymphomas, but the tumors derived are aggressive activated DLBCL-like lymphomas rather than BLs." (PMID 38620028, 2024). "While CD40 is known to activate non-canonical NF-κB signaling component RelB, which has been shown to control BCLXL expression in related hematological malignancies, the control of MCL1 by specific NF-κB subunits is less clear, particular in the context of lymphoma." (PMID 40819126, 2025).